CCSER1 (coiled-coil serine rich protein 1)
Synonyms: FAM190A; KIAA1680
Tractability: PROTAC: ubiquitination databases record sites on it.
Gene: Protein-coding gene on chromosome 4 (90,127,394 to 91,605,295, forward strand). Ensembl gene ENSG00000184305.
Gene Ontology:
Molecular function: protein binding
Genetic constraint (gnomAD): Loss-of-function variants: 25 observed, 59.22 expected, observed/expected ratio (o/e) 0.42, 90% interval 0.31 to 0.59. The upper end of that interval is the gene's LOEUF score, 0.59, which puts it in group 2 of 6, group 1 being the genes least tolerant of losing a copy. Missense variants: 983 observed, 970.85 expected, observed/expected ratio (o/e) 1.01, 90% interval 0.96 to 1.07. Synonymous variants: 376 observed, 353.59 expected, observed/expected ratio (o/e) 1.06, 90% interval 0.98 to 1.16.
Homologues: Orthologues: chimpanzee CCSER1 (99% identical), macaque CCSER1 (98% identical), dog CCSER1 (91% identical), pig CCSER1 (89% identical), rabbit CCSER1 (87% identical), rat Ccser1 (79% identical), mouse Ccser1 (79% identical), guinea pig CCSER1 (54% identical), tropical clawed frog ccser1 (44% identical), zebrafish ccser1 (36% identical). Paralogues in human: CCSER2 (17% identical).
Diseases named in the same sentence as CCSER1 in open-access papers:
CCSER1 is named in the same sentence as 15 diseases in open-access papers, as found by Europe PMC text mining. Sharing a sentence is not in itself a finding about the gene and the disease. The quoted sentences say what the papers report.
adenoma (2 papers, 2021 to 2023). A neoplasm arising from the epithelium. "Furthermore, analysis of genetic sequencing has identified genetic variations (e.g., in LINC01605, PROKR2, and CCSER1 genes) linked to constituents of the metabolome or microbiome, as well as the risk of adenoma or colorectal cancer." (PMID 37012201, 2023).
colorectal cancer (2 papers, 2022 to 2023). A primary or metastatic malignant neoplasm that affects the colon or rectum. "CCSER1 was reported to be involved in the cell division defect with a potential impact on microbiome components in human colorectal cancer." (PMID 36102532, 2022).
cognitive decline (1 paper, 2022). "CCSER1 (coiled-coil serine rich protein 1) is one of the genes influencing the rate of cognitive decline in patients with AD." (PMID 36005139, 2022).
colon cancer (1 paper, 2025). "CCSER1, along with other genes like FHIT, was found to play a significant role in genome stability and the cell division of colon cancer." (PMID 40870036, 2025).
diabetes (1 paper, 2021). "In individuals with diabetes, rs116405693 at the CCSER1 (coiled-coil serine rich protein 1) locus was associated with PAD (odds ratio [95% CI], 1.51 [1.32–1.74], Pdiabetes=2.5×10−9, Pinteractionwithdiabetes=5.3×10−7)." (PMID 34601942, 2021).
Infertility (1 paper, 2024). "Some of the genes presented, such as CCSER1, GNAQ, NCOA2, SNRK, and TSPO, have been previously associated with fertility traits in livestock species or related to infertility in human patients (CEP78 and GPER1)." (PMID 38540441, 2024).
cancer (7 papers, 2011 to 2023). A tumor composed of atypical neoplastic, often pleomorphic cells that invade other tissues. "Deficiency of the coiled-coil serine rich protein 1 has been already associated with a cell division defect in humans and several human cancers." (PMID 31749836, 2019). "We propose that in cancer, FDs are able to remove genetic elements which in cis keep at bay the expression of “dormant” oncogenes, such as CCSER1 in the case described herein." (PMID 34187875, 2021). "Within the most frequent CFS in this group, FRA4F, which is deleted in up to 18% of cancer cases and harbours the CCSER1 gene, we identified a region which includes an intronic, antisense pseudogene, TMSB4XP8." (PMID 34187875, 2021). "The coiled-coil serine rich protein 1 or CCSER1 gene on OAR6, which encodes a proline-rich protein, plays an important role in mitosis and cell division and has been linked to several human cancers." (PMID 37932811, 2023). "Notably, the CCSER1 gene has also been studied in cancer therapy." (PMID 38231770, 2023). "Interestingly, most of these common candidates are large cancer genes within fragile sites, such as FHIT, WWOX, CCSER1, IMMP2L, CDKN2A, and CDKN2B26,44–47." (PMID 36163358, 2022).
Tumor (2 papers, 2011 to 2021). "We found that tumours presenting CCSER1 deletions presented consistently higher levels of expression in the remaining 5′ and 3′ portions of the gene, compared with patients with wild-type CCSER1." (PMID 34187875, 2021).
CCSER1 also shares sentences with these, for which no sentence is quoted: adenocarcinoma (1 paper); atherosclerosis (1); cervical cancer (1); juvenile polyp (1); juvenile polyposis syndrome (1); melanoma (1); Parkinsonism (1).